CXCR4 (C-X-C motif chemokine receptor 4)
Diseases named in the same sentence as CXCR4 in open-access papers (continued):
Sharing a sentence is not in itself a finding about the gene and the disease.
breast carcinoma (continued). "An anti-CXCR4 antibody, or peptides recognizing CXCR4, have also been tested to target cytotoxic substances against cancer stem cells in acute myelogenous leukemia, breast cancer cells, colorectal cancer cells and multiple myeloma." (PMID 33467722, 2021). "To dissect the factors that play a key role in suppressing bone tropic breast cancer migration by ATP, we decided to explore CXCR4, a α-chemokine receptor for CXCL12 ligand." (PMID 34503103, 2021). "Targeting a single paracrine signaling pathway, e.g., CCL21/CCR7 or CXCL12/CXCR4, has been shown to reduce lymphatic metastasis in murine models of breast cancer." (PMID 34885152, 2021). "We first validated the PLA approach for the detection of endogenous CXCR4 and CCR7 association in breast cancer cells lines, differing in their invasive phenotype." (PMID 34685420, 2021). "More importantly, our awareness remained toward rewiring the possible gene effectors involving in elevated level of CXCR4 during malignant progression of breast cancer." (PMID 34070538, 2021). "Inhibition of dipeptidyl peptidase (DPP)-4 stimulated CXCL12/CXCR4 expression and activated mTOR signaling, which further induced epithelial-mesenchymal transition of breast cancer cells and metastasis." (PMID 34234860, 2021). "Another study shows that mice form much smaller tumor masses when inoculating breast cancer cells with low CXCR4 expression." (PMID 34503103, 2021). "Both ATPγS and BzATP suppressed the expression of CXCR4, a chemokine receptor known to promote breast cancer bone metastasis, and knocking down CXCR4 expression by siRNA attenuated the inhibitory effect of ATPγS on cancer cell migration." (PMID 34503103, 2021). "The CXCL12/CXCR4 axis plays a pivotal role in homing and invasion of bone-metastatic breast cancer cells." (PMID 34064589, 2021). "The CXCR4 antagonist, balixafortide in combination with eribulin, is currently being tested in a phase I clinical trial to only reduce breast cancer metastasis and improve chemotherapy efficacy." (PMID 34944738, 2021). "We have previously found that in a panel of human breast cancer cell lines, the coupling of Gαi and Gβ proteins with CXCR4 varies significantly between cell lines with different invasive properties." (PMID 34685420, 2021). "Potential therapeutic strategies have been developed by targeting CXCR4 or its ligand, and efficacy has been shown in inhibiting primary tumor growth and metastasis of breast cancer." (PMID 34503103, 2021). "A CXCL12/CXCR4 interaction drives breast cancer metastasis, as evidenced by a direct correlation between high CXCR4 levels in primary tumors and high metastatic capacity." (PMID 33530455, 2021). "Several studies have assessed the impact of CXCR4 in breast cancer cell survival, proliferation, angiogenesis, migration, and metastasis." (PMID 33747948, 2021). "CXCR4 is known to drive breast cancer metastasis to bone through engagement with its cognate ligand, CXCL12, which is highly expressed on mesenchymal stromal cells in the bone marrow." (PMID 34556788, 2021). "The cross-link between CXCR4 and other pathways such as Notch, Wnt, and SHH is also associated with increased breast cancer growth." (PMID 33747948, 2021). "In breast cancer, CXCR4 overexpression promotes tumor cell dissemination to the lungs and lymph nodes while in melanoma, CXCR4 induces lung metastases but not lymph nodes dissemination." (PMID 33937018, 2021). "In breast cancer cells, siRNA targeting CXCR4 inhibited the migration of breast cancer cells in vitro." (PMID 34447750, 2021). "High RANK expression (the receptor for RANKL) in the tumors of breast cancer patients was associated with poor prognosis and the combined expression of RANK and CXCR4 in breast cancer patients predicted recurrence of bone metastases." (PMID 34207620, 2021).
breast carcinoma (continued). "After demonstrating activation of the oncogenic MAPK pathway by knocking down CXCR4 expression, we investigated phenotypic changes in MCF7 breast cancer cells co-cultivated with THP-1 cells expressing reduced levels of CXCR4." (PMID 35111484, 2021). "Ablation of CXCR4 in breast cancer cells was further shown to inhibit bone metastasis in a mouse model by attenuating the PI3K/AKT/matrix metallopeptidase 9 (MMP9) axis." (PMID 34064589, 2021). "CXCR4 expression promotes breast cancer cell migration towards sites of potential metastasis that actively secrete CXCL12, the ligand of CXCR4, whose production is increased during tumor-promoting processes, such as angiogenesis and inflammation." (PMID 34830776, 2021). "A99mTc-labeled siRNA was used to target CXCR4 in breast cancer xenografts for tracing the delivery of siRNAs in vivo." (PMID 33986665, 2021). "In preclinical studies, tumor uptake of 64Cu-AuNCs-AMD3100 correlated with CXCR4 expression in both primary lesions and lung metastases of a mouse 4T1 orthotopic breast cancer model." (PMID 34771622, 2021). "Upregulation of CXCR4 has been noted in various cancers, including breast cancer, gastric cancer, non-small cell lung cancer (NSCLC), and renal cell carcinoma." (PMID 34500609, 2021). "In this study, we validated the potential function of miR-139/CXCR4 in p-Akt inactivation that influence the advanced disease phenotype in breast cancer cells." (PMID 34070538, 2021). "CAFs have been reported to recruit ECs and CD4+CD25+ T cells to the CSC niche in human breast cancer along the CXCL12/CXCR4 axis." (PMID 33530455, 2021). "CXCR4, as the most common chemokine receptor, is responsible for numerous malignancies, including breast cancer, melanoma, prostate cancer, and GC." (PMID 33692828, 2021). "CXC chemokine receptor 4 (CXCR4), a 352 amino acid rhodopsin-like GPCR was first investigated as chemokine receptor associated with breast cancer metastasis to the lung tissues." (PMID 34298991, 2021). "CXCR4 is a chemokine receptor, which is highly expressed in breast cancer patients, and high expression indicates a poor prognosis." (PMID 34759953, 2021). "Recent studies using the bone metastatic MDA-231 breast cancer cell line have shown that CXCR4 was over expressed in single cell clones which metastasize to the bone relative to the parental population." (PMID 34503118, 2021). "High levels of CXCR-4 were found in breast cancer cells, which is believed to indicate the metastatic destination of tumor cells." (PMID 33854604, 2021). "Our work further demonstrates that the receptor CXCR4 expressed in macrophages is important for breast cancer cell growth and migration." (PMID 35111484, 2021). "Breast cancer cell nuclear and cytoplasm expressions of CXCR4 protein were examined using immunohistochemistry." (PMID 33773539, 2021). "A recent study supported the key role of CXCR4 signaling in enhancing breast cancer tumorigenesis and invasiveness." (PMID 34070538, 2021). "For example, the expression of LSINCT5 in primary breast cancer tissues is ten times higher than that in normal tissues, which enhances the invasion of breast cancer cells via chemokine receptor (CXCR4)." (PMID 34057025, 2021). "Investigate the effect of SDF1a, nuclear, and cytoplasmic CXCR4 breast cancer tissue on metastasis and overall survival in patients with complete-chemotherapy and no-chemotherapy." (PMID 33773539, 2021). "TN1, a peptide that simulates the CXCL12 recognition site for CXCR4 and acts as a competitive antagonist, was modified to reduce its toxicity and increase its stability and is now used for breast cancer treatment." (PMID 33530455, 2021). "In this study, we investigated the role of CXCR4 expressed in TAMs on breast cancer cell migration by reducing CXCR4 expression via CRISPR-CAS9 system in differentiated THP-1 cells (a TAMs model)." (PMID 35111484, 2021).
breast carcinoma (continued). "It has already been established that SDF-1α and its receptor CXCR4 are expressed in breast cancer cells and that their activation contributes to angiogenesis and the successive steps of metastasis." (PMID 33919589, 2021). "CXCR4 can be a key regulator in the cross-talk between breast cancer cells and TAMs promoting migration." (PMID 35111484, 2021). "Together with our earlier observations in primary mammary tumour cells, these results suggest that functional CXCR4 and CCR7 heterodimers are present at the later invasive stage of cancer progression." (PMID 34685420, 2021). "For example, matrine suppresses the migration and invasion capacities of lung, prostate, and breast cancer cells via downregulating the levels of C-X-C motif chemokine receptor 4 (CXCR4)." (PMID 33066509, 2020). "Human breast cancer cells express more CXCR4/RANK than normal epithelial cells, and CXCL12, the receptor of CXCR4, is highly expressed in the liver, lung, and bone marrow." (PMID 32117996, 2020). "LMWHs also inhibit CXCR4 in breast cancer mouse models, while CXCR4 inhibition also mitigates desmoplasia and enhances T cell infiltration, rendering metastatic breast cancer more susceptible to immunotherapy." (PMID 32069809, 2020). "In breast cancer, CXCR4 is overexpressed and is responsible for metastasis to predilection sites in the body that are enriched for CXCL12 including the lungs, bone marrow and brain." (PMID 32872485, 2020). "Upon ligand activation PPAR-γ recruits transcriptional corepressor SMRT onto the CXCR4 promoter in both stromal and breast cancer cells." (PMID 33096815, 2020). "Although CXCL12/CXCR4 inhibition brings promising results in breast cancer trials, systemic effects of blocking CXCR4 such as alterations in the spleen remain poorly understood." (PMID 33096815, 2020). "CXCR4 is over-expressed in different cancer cells and is considered as a prognostic marker of various cancers including breast cancer, ovarian cancer, leukemia, prostate cancer, and colorectal cancer." (PMID 33392074, 2020). "CXCR4 inhibitors have been reported promising therapeutic effects on solid tumors, including glioblastoma, breast cancer and mesothelioma." (PMID 33414786, 2020). "A previous study in MCF7 breast cancer cells also demonstrated that 5-aza treatment demethylated the CXCR4 promoter and concomitantly increased CXCR4 mRNA expression." (PMID 32110952, 2020). "CXCR4 remains crucial in breast cancer metastasis pattern to the lungs, liver, bones and lymph nodes since these metastatic niches express high levels of its ligand CXCL12." (PMID 33096815, 2020). "Given this dichotomy between the physiological and pathophysiological functions of CXCR4, we examined CXCR4 expression in breast cancer cells and found that it was upregulated by leptin." (PMID 32836215, 2020). "On the one hand, miR-381 inhibits Cx43 and CXCR4, which can regulate metastasis and cell migration in breast cancer." (PMID 33324542, 2020). "Other CXCR4-targeting therapeutic strategies in breast cancer aim at inhibiting CXCR4-dependent migration, invasion and metastasis." (PMID 33096815, 2020). "In our previous study, we demonstrated that deficiency in DPP-4 induced EMT in 4T1 cells, MCF-7 cells and MDA-MB-231 cells and accelerated lung metastasis of breast cancer in vivo via the CXCL12/CXCR4/mTOR axis." (PMID 31991851, 2020). "In breast cancer, the CXCL12/CXCR4 axis is implicated in the homing of cancer cells to metastatic sites." (PMID 32079335, 2020). "When coming to address the roles of CXCL12 in mediating tumor-stroma interactions in breast cancer, the majority of studies indicated that this chemokine or CXCR4 stand in the center of tumor-promoting cross-talks between cancer cells and stromal cells." (PMID 32582148, 2020).
breast carcinoma (continued). "P-Rex1 is activated by human epidermal growth factor receptor (HER2) and GPCRs, such as the chemokine receptor CXCR4 in breast cancer, and overexpressed in ER and HER2 positive luminal A and B breast cancer tissues compared to normal breast tissue." (PMID 32322580, 2020). "High levels of CXCL12 and CXCL16 in CAFs from human brain cancer metastasis attract breast cancer cells via the CXCR4/CXCL12 and CXCR6/CXCL16 pathways." (PMID 33096815, 2020). "Having confirmed the important role of the SDF-1/CXCR4 axis in directional chemotaxis of breast cancer cells from breast to bone tissues, we performed real-time PCR assays to analyze SDF-1 expression in human bone marrow." (PMID 32836215, 2020). "First, we believe that computational approaches aiming to explore high-throughput data will generate novel basic knowledge about CXCL12/CXCR4 signaling in breast cancer." (PMID 33096815, 2020). "CXCR4 has been the first chemokine receptor found hijacked by breast cancer cells to proliferate and metastasize to distant organs." (PMID 33096815, 2020). "In conclusion, SETDB2 interacts with ΔNp63α, methylates and stabilizes ΔNp63α to upregulate the transcription of the Hedgehog signaling pathway-associated genes CXCR4, PTCH1 and GLI2, which promote breast cancer stem cell maintenance and tumor initiation." (PMID 32549764, 2020). "CXCL12 secreted by carcinoma-associated fibroblasts (CAFs) stimulates tumor growth directly, acting through CXCR4 expressed by breast cancer cells and promoting invasiveness." (PMID 33363463, 2020). "Intriguingly, hypoxia stimulates CXCR4 expression in breast cancer, thereby promoting homing of metastatic breast cancer cells." (PMID 32092997, 2020). "The hepatocyte growth factor (HGF)/c-MET axis and the stromal cell-derived factor-1 (CXCL12)/C-X-C chemokine receptor type 4 (CXCR4) axis are prognostic in women with breast cancer." (PMID 32188473, 2020). "A phase I trial (NCT01837095) with CXCR4 antagonist Balixafortide and Eribulin chemotherapy evaluated the safety, tolerability, pharmacokinetics and efficacy in heavily pretreated, relapsed breast cancer patients." (PMID 33414786, 2020). "AMD3465 is a potent inhibitor with high specificity for CXCR4, which has been shown to strongly inhibit CXCR4 function in breast cancer." (PMID 32872485, 2020). "The CXCL12/CXCR4 signaling in breast cancer cells also induces resistance to immune checkpoint blockers." (PMID 33096815, 2020). "CD24 regulates the activity of the chemokine receptor CXCR4 by affecting its localization in the plasma membrane lipid rafts of pre‐B cells and breast carcinoma cells." (PMID 32394616, 2020). "For example, Ixabepilone, which was associated with CD40, CXCR4, IL6, and SERPINE1, were used in locally advanced breast cancer and metastatic breast cancer, can potentially be repurposed to treat OCSCs." (PMID 32977853, 2020). "Cell membrane localization mostly reflects the activated state of the chemokine receptor and has been associated with a worse prognosis in esophageal cancer for CXCR7 and in gastric and breast cancer for CXCR4 especially due to enhanced metastasis." (PMID 33281749, 2020). "In summary, CXCR4 overexpression in breast cancer induces ERK activation, proliferation and drug resistance." (PMID 33096815, 2020). "Post-transcriptional regulation of CXCR4 was reported in breast cancer, where the oncogene Her2 blocks its ubiquitination and degradation." (PMID 32260318, 2020). "Taken together, our findings suggest that DPP-4 inhibitors potentiate chemotherapy resistance via the induction of ABC transporters by the CXCL12/CXCR4/mTOR/TGFβ signaling pathway in breast cancer cells." (PMID 31991851, 2020). "We therefore explored the role of the SDF-1/CXCR4 axis in leptin-mediated bone metastasis of breast cancer cells." (PMID 32836215, 2020).
breast carcinoma (continued). "ANGPTL2 and IL-6 enhance the reaction of breast cancer cells to bone-derived CXCL12 through the upregulation of CXCL12 receptor CXCR4 in these cancer cells, respectively." (PMID 33123472, 2020). "On the other hand, other drugs with cyclophosphamide, indicated for the treatment of cancerous diseases such as breast cancer and cervical cancer, induce the cell surface expression of CXCR4 and enhance the migration of MDA-MB-231 cells." (PMID 33195200, 2020). "TQ was also shown to inhibit bone metastasis of breast cancer cells through abrogation of the CXCR4 signaling axis." (PMID 32821342, 2020). "It has been reported that CXCR4 density, organization, cholesterol content, and matrix stiffness affect the unbinding force of CXCR4 in breast cancer." (PMID 32483419, 2020). "CXCR4 increases the growth and sphere formation efficiency of hypoxic breast cancer side population (SP) cells by c-Jun/ABCG2 pathway." (PMID 32232002, 2020). "It is also interesting to note that CXCR4, another chemokine receptor, shows a higher expression in breast cancer tissue, whereas its ligand CXCL12 is downregulated in the same tissue, which is in contrast to the situation observed for CXCR2." (PMID 32727083, 2020). "In our previous study, we have confirmed that DPP-4 inhibition induced the EMT through the CXCL12/CXCR4/mTOR axis in breast cancer." (PMID 31991851, 2020). "To date, it has been reported that the expression of CXCR4, CCR7, and CCR10 was associated with breast cancer metastases." (PMID 33244467, 2020). "In summary, CXCL12/CXCR4 signaling acts as a master regulator of breast cancer metastasis and mediates metastasis to all target organs such as brain, lungs, lymph nodes, liver and bones." (PMID 33096815, 2020). "We have recently shown that a DPP-4 inhibitor accelerated the epithelial mesenchymal transition (EMT) and lung metastasis via the CXCL12/CXCR4/mTOR axis in breast cancer cells." (PMID 31991851, 2020). "Several studies found that the SDF-1/CXCR4 axis played an important role in regulating the metastasis of breast cancer to specific organs." (PMID 32836215, 2020). "As NF-κB binding site has been reported to be closely located within CXCR4 promoter and can modulate CXCR4 levels in breast cancer cells, we also investigated the impact of matrine NF-κB down regulation in this report." (PMID 32630806, 2020). "Members of the nuclear receptor superfamily such as estrogen receptor (ER) α and β also regulate the transcription of the CXCL12/CXCR4 cascade components in breast cancer." (PMID 33096815, 2020). "Breast cancer lymph node positive patients show increased infiltration of plasmacytoid DCs and this correlates with the percentage of CXCR4 positive cells." (PMID 33096815, 2020). "In breast cancer, CXCR4 promotes metastasis to organs like bone, liver, and lung, sites commonly affected by metastatic breast cancer, where its ligand, C-X-C motif chemokine 12 (CXCL12), is expressed in large quantities." (PMID 32075106, 2020). "CXCR4 is highly expressed in some breast cancer cells, whereas SDF‐1α is expressed in the brain and lungs, which causes the breast cancer cells extravasating into the lungs more likely form brain metastasis." (PMID 32945619, 2020). "We show that the CXCL12/CXCR4 cascade is involved in nearly every aspect of breast cancer tumorigenesis including proliferation, cell motility and distant metastasis." (PMID 33096815, 2020). "The CXCL12/CXCR4 signaling pathway has emerged in the recent years as a key player in breast cancer tumorigenesis." (PMID 33096815, 2020). "Researcher found that CXCR4 was upregulated in colorectal cancer and breast cancer 38, 39, overexpressed CXCR4 promoted the proliferation and invasion of ovarian cancer." (PMID 33123295, 2020). "CXCR4 density, spatial organization, and matrix stiffness are paramount to achieve strong binding in breast cancer." (PMID 32483419, 2020).